SETBP1 (SET binding protein 1)
Diseases named in the same sentence as SETBP1 in open-access papers (continued):
Sharing a sentence is not in itself a finding about the gene and the disease.
acute myeloid leukemia (17 papers, 2012 to 2025). Acute myeloid leukemia (AML) is a group of neoplasms arising from precursor cells committed to the myeloid cell-line differentiation. "SETBP1 is a well-established candidate gene harboring somatic mutation in various myeloid malignancies including secondary acute myeloid leukemia (sAML) and chronic myelomonocytic leukemia (CMML)." (PMID 30134812, 2018). "These SETBP1 mutations have rarely been identified in non‐secondary acute myeloid leukemia." (PMID 37489294, 2023). "In addition, other studies have claimed that SETBP1 expression is associated with acute myeloid leukemia and that microRNA-211-5p directly targets SETBP1 to inhibit triple-negative breast cancer cell proliferation, migration and metastasis." (PMID 35433683, 2022). "SETBP1 is overexpressed in 27.6% of acute myeloid leukemia at diagnosis and is associated with poor prognosis, particularly in elderly patients, as patients with SETBP1 overexpression had a significantly shorter overall survival and event-free survival in patients over 60 years." (PMID 24307892, 2013). "Gain-of-function somatic mutations of SET binding protein 1 (SETBP1) result in the accumulation of SETBP protein and are detected in 17% of secondary acute myeloid leukemia (AML) patients." (PMID 39104425, 2024). "Patients with aCML are at significant risk of developing Acute Myelogenous Leukemia (AML), particularly with mutations in genes such as SETBP1, NRAS, and ASXL1." (PMID 39769254, 2024). "Case presentation: In this study we described a patient who underwent hematopoietic stem cell transplantation due to acute myeloid leukemia and subsequently developed triple-negative myeloproliferative neoplasms with mutations in the ASXL1, SETBP1 and EZH2 genes 9 years later." (PMID 39907609, 2025). "Here, we present a case of a patient who underwent hematopoietic stem cell transplantation (HSCT) due to acute myeloid leukemia (AML) and developed from donor cells triple-negative (TN) myeloproliferative neoplasms with mutations in the ASXL1, SETBP1 and EZH2 genes." (PMID 39907609, 2025). "SETBP1 has been reported to be overexpressed in acute myeloid leukemia (AML), protecting the SET protein from proteasome degradation, and leading to increased levels of full-length SET protein." (PMID 35898891, 2022). "For example, acute myeloid leukaemia (AML) patients with normal karyotype have their PP2A predominately inhibited by CIP2A, while patients with an adverse karyotype have their PP2A inhibited by SETBP1." (PMID 33947031, 2021).
leukemia (15 papers, 2015 to 2025). A malignant (clonal) hematologic disorder, involving hematopoietic stem cells and characterized by the presence of primitive or atypical myeloid or lymphoid cells in the bone marrow and the blood. "The overexpression of SETBP1 promotes the proliferation of leukemia and is closely associated with poor overall survival (OS) in patients with AML, specifically elderly patients." (PMID 36674828, 2023). "Mutant SETBP1 enhanced the activity of the MYC pathway to facilitate CSF3R-related myeloproliferative neoplasms, and the NRAS-driven MAPK signal was activated by mutated SETBP1 to accelerate aggressive leukemia." (PMID 37535001, 2023). "Despite the overlap between the mutations present in hematological disorders and in SGS, recent data suggest that somatic SETBP1 mutations found in leukemias are more disruptive to the degron than germline variants responsible for the onset of SGS11." (PMID 29875417, 2018). "Genes controlled by SETBP1 such as MECOM are significantly upregulated in leukemias containing SETBP1 mutations." (PMID 29875417, 2018). "Again it was clear that SETBP1 mutations have a significantly higher oncogenic potential than wild-type SETBP1, triggering leukemia with a shorter latency and greater penetrance." (PMID 28881700, 2017). "Drawing on previous studies of somatic SETBP1 mutations in leukemia, our results reveal a genotype-phenotype correlation in germline SETBP1 mutations spanning a molecular, cellular and clinical phenotype." (PMID 28346496, 2017). "SETBP1 mutations in MDS/MPN overlap syndrome is associated with accelerated transformation to leukemia and poor prognosis." (PMID 29225884, 2017). "All SETBP1 degron mutations identified in leukemia were compared to mutations observed in SGS on their effect on the SETBP1-βTrCP1 interaction using in silico modeling." (PMID 28346496, 2017). "As expected, high levels of mutant Setbp1 proteins were detected in these leukemias, confirming their causal role in leukemia induction in these mice." (PMID 27863435, 2016). "SETBP1 overexpression is associated with accelerated transformation to leukemia and poor prognosis." (PMID 29225884, 2017). "Overlapping SETBP1 hotspot mutations have been observed recurrently as somatic events in leukemia." (PMID 28346496, 2017). "Experimental mouse models reveal that high-level expression of BCR::ABL alone is insufficient to induce leukemia, whereas co-expression with Setbp1, Hoxa10 or Hoxa9 produces aggressive leukemia within 3 weeks." (PMID 41179655, 2025). "Activation of SETBP1 had been shown to contribute to the maintenance of leukemia stem cell self-renewal and the promotion of leukemia development through the inhibition of PP2A in myeloid leukemias." (PMID 39054337, 2024). "Substitutions in SETBP1 residue I871 result in a weak increase in protein levels and mutations affecting this residue are significantly more frequent in SGS than in leukemia." (PMID 28346496, 2017). "In contrast with SETBP1 mutations, germline PTPN11 mutations causative for Noonan syndrome rarely overlap with somatic mutations observed in leukemia." (PMID 28346496, 2017). "In vitro treatment with these inhibitors has been demonstrated to lead to an efficient differentiation of SETBP1 activation-induced leukemia cells, and to significantly extend the survival of mice transplanted with such leukemias." (PMID 28881700, 2017). "Different from GMP-derived leukemias induced by Setbp1 and BCR/ABL, Hoxa9+BCR/ABL and Hoxa10+BCR/ABL leukemias are mostly monoclonal in origin, suggesting that additional mutation(s) is likely required for the transformation in both cases." (PMID 29228732, 2017). "We analyze the distribution and magnitude of effect of germline and somatic SETBP1 mutations in SGS and leukemia, respectively." (PMID 28346496, 2017).
leukemia (continued). "Given the occurrence of overlapping germline and somatic SETBP1 mutations, we compare the mutations in SGS and leukemia to identify genetic and functional differences between SETBP1 mutations in both conditions." (PMID 28346496, 2017). "SETBP1 mutations with weak effect are almost exclusively germline events, while strongly activating SETBP1 mutations occur both in SGS and leukemia." (PMID 28346496, 2017). "Consistent with our studies in immortalized cells, high levels of Myb protein were detected in leukemias induced by wild-type Setbp1 and Setbp1 missense mutants." (PMID 27863435, 2016). "Similar to leukemia cells induced by wild-type Setbp1, only a small fraction of these cells are positive for c-kit and Sca-1." (PMID 27863435, 2016). "The human SETBP1 gene, originally called SEB, is located at the cytogenetic band q12.3 of chromosome 18, a region that contains candidate tumor suppressor genes associated with deletions in cancer and leukemia." (PMID 28881700, 2017). "We harvested leukemia cells from secondary recipient mice that have been transplanted with leukemia cells induced by wild-type Setbp1, Setbp1(D/N), or Setbp1(I/T), and transduced them immediately with lentivirus containing either a Myb-specific shRNA or a non-targeting shRNA." (PMID 27863435, 2016). "SETBP1 mutations disrupt the degron motif of the protein, resulting in an impaired proteasome cleavage and subsequent SETBP1 protein accumulation, which further enhances the inhibitory effects of SET over PP2A and support leukemia cell proliferation." (PMID 35267643, 2022). "In JMML, the observation that SETBP1 mutations occur only in a subpopulation of leukemic cells prompted the view that they may be involved in the evolution rather than at the beginning of leukemia, and are associated with a dismal prognosis." (PMID 28881700, 2017). "Since SETBP1 missense mutants have been shown to induce greater PP2A inhibition than wild-type SETBP1, it is possible that increased PP2A inhibition by Setbp1 mutants may also contribute significantly to faster leukemia development in our study." (PMID 27863435, 2016). "Myb knockdown in mouse leukemias induced by wild-type and mutant Setbp1 was not able to induce dramatic extension of recipient survival in our study." (PMID 27863435, 2016). "In addition, a significantly higher HOXA9 and HOXA10 expression levels were observed in SETBP1-mutant leukemias in comparison with wild-type cases without SETBP1 overexpression." (PMID 25763353, 2015).
chronic neutrophilic leukemia (14 papers, 2014 to 2025). A rare chronic myeloproliferative neoplasm characterized by neutrophilic leukocytosis. "Although the presence of mutations in SETBP1 supports the diagnosis of aCML, the overall mutation profile is similar to that of chronic neutrophilic leukemia, CMML, and MDS/MPN-U." (PMID 39337700, 2024). "SETBP1 mutations have been shown to be a poor prognostic factor in chronic neutrophilic leukemia (CNL) which is a rare myeloproliferative leukemia." (PMID 37489294, 2023). "Recurrent mutations of SETBP1 gene are detected in about 80 % of patients with chronic neutrophilic leukemia (CNL) and in about 25 % of patients with atypical chronic myeloid leukemia." (PMID 26019984, 2015). "Mutations in CSF3R, SETBP1 and CALR are reported in patients with chronic neutrophilic leukemia (CNL)." (PMID 25316523, 2014). "This meta-analysis investigates the prognostic effect of SET binding protein 1 (SETBP1) mutations in patients with myelodysplastic syndromes (MDS), chronic myelomonocytic leukemia (CMML), or chronic neutrophilic leukemia (CNL)." (PMID 28158286, 2017). "SETBP1 mutations are also detected in myelodysplastic syndromes (MDS), chronic myelomonocytic leukemia (CMML), and chronic neutrophilic leukemia (CNL)." (PMID 28158286, 2017).
chronic myeloid leukemia (13 papers, 2013 to 2024). "SETBP1 variants occur as somatic mutations in several hematological malignancies such as atypical chronic myeloid leukemia and as de novo germline mutations in the Schinzel–Giedion syndrome." (PMID 29875417, 2018). "For instance, somatic SETBP1 mutations have been associated mainly with chronic myeloid leukemia, a disease occurring generally in individuals above the age of 60." (PMID 28346496, 2017). "SETBP1 mutations have been identified in atypical chronic myeloid leukemia (aCML), which is a rare disorder of hematopoietic stem cells and shares clinical and laboratory features with CML but lacks the BCR-ABL fusion gene." (PMID 28533818, 2017). "Recently, by exome sequencing technology, SETBP1 mutations were found to recur frequently in patients with atypical chronic myeloid leukemia (aCML), a disorder with overlapping clinical features with CML but without the typical Ph1 translocation." (PMID 25763353, 2015). "SETBP1 mutations are observed in atypical chronic myeloid leukemia." (PMID 27959900, 2016). "MDS/MPN with neutrophilia (formerly atypical chronic myeloid leukemia, BCR::ABL-negative) can demonstrate eosinophilia in addition to leukocytosis, neutrophilic dysplasia, and frequent mutations involving SETBP1." (PMID 38611061, 2024). "Atypical chronic myeloid leukemia (aCML) is most known for granulocytosis with marked dysplasia and often harbors ASXL1 mutations, but SETBP1 and ETNK1 are more specific to this disease." (PMID 35844680, 2021). "Overexpression of SETBP1 had been identified in 30% of patients with AML and chronic myeloid leukemia (CML) patients in blast crisis." (PMID 39054337, 2024). "In hematologic neoplasms, the discovery of SETBP1 as a new oncogene has helped to better define the molecular characteristics of pathologies such as atypical Chronic Myeloid Leukemia (aCML), a disease initially defined only by negative characteristics, like the absence of BCR-ABL1 fusion." (PMID 28881700, 2017).
chronic myelomonocytic leukemia (13 papers, 2014 to 2024). A myelodysplastic/myeloproliferative neoplasm which is characterized by persistent monocytosis, absence of a Philadelphia chromosome and BCR/ABL fusion gene, fewer than 20 percent blasts in the bone marrow and blood, myelodysplasia, and absence of PDGFRA or PDGFRB rearrangement. "Two patients with SETBP1-mutated and ASXL1-unmutated developed AML transformation, whereas two other patients with ASXL1-mutated and SETBP1-unmutated evolved into chronic myelomonocytic leukemia (CMML) in their study." (PMID 33822276, 2021). "Somatic mutations of SETBP1 resulted in gain-of-function were associated with poor prognosis and myeloid leukemic transformation in patients with myelodysplastic syndromes (MDS) and chronic myelomonocytic leukemia (CMML)." (PMID 37150818, 2023).
Intellectual disability (12 papers, 2015 to 2025). "We consider this a potential molecular mechanism explaining the link between the SETBP1 frameshift variant and mental retardation." (PMID 37798664, 2023). "Furthermore, the loss‐of‐function mutations in SETBP1 have also been reported to be associated with intellectual disability, expressive language disorders, childhood aphasia, autism spectrum disorders, neurodevelopmental disorders, and developmental epileptic encephalopathy." (PMID 37489294, 2023). "TGex analysis (LifeMap Sciences, USA) prioritized 9 candidate variants across 7 genes (MED13, POGZ, SETBP1, SCN9A, SCO1, APTX, TIE1) associated with phenotypes including congenital megacolon, intellectual disability, motor delay, and developmental delays." (PMID 41195223, 2025). "Clinical findings present in most SETBP1-HD individuals include: motor developmental delay (97%); developmental delay/mild-to-severe intellectual disability; learning difficulties; speech and language disorder (including childhood apraxia of speech)." (PMID 39350244, 2024). "SETBP1 Haploinsufficiency Disorder (SETBP1-HD) is characterised by mild to moderate intellectual disability, speech and language impairment, mild motor developmental delay, behavioural issues, hypotonia, mild facial dysmorphisms, and vision impairment." (PMID 39350244, 2024). "Targeted NGS analysis of the intellectual disability multigene panel highlighted the presence of the frameshift deletion c.2199_2203del; p.Glu734Alafs19* in SETBP1." (PMID 33391157, 2020). "Interestingly, loss of function mutations in SET also lead to a clinical phenotype including intellectual disability, developmental and speech delay and motor impairment, similar to SETBP1-HD." (PMID 39350244, 2024). "SETBP1 (SET‐binding protein 1/SEB/MRD29), identified as SET‐binding protein, is the causative gene of Schinzel–Giedion syndrome, which is characterized by severe intellectual disability and a distorted facial appearance." (PMID 37489294, 2023). "In addition, germline loss-of-function mutations in the SETBP1 gene are correlated with developmental delay, which has a spectrum of symptoms, including absent speech/expressive language delays and mild-severe intellectual disability." (PMID 36161179, 2022). "Of the genetic defects found outside the MD gene panel, seven genetic defects were found in genes present in the intellectual disability gene panel (ARID1B, SCN1A, ASPM, CTNNB, KDM6A, SMARCA4 and SETBP1)." (PMID 25735936, 2015). "Additionally, large scale targeted sequencing within large umbrella cohorts, such as intellectual disability (ID), ASD, and epilepsy allowed to expand the spectrum of SETBP1-related disorders." (PMID 33391157, 2020).
myelodysplastic syndrome (11 papers, 2017 to 2025). A clonal hematopoietic disorder characterized by dysplasia and ineffective hematopoiesis in one or more of the hematopoietic cell lines. "ASXL1 is an epigenetic regulator and the mutations in ASXL1 gene often coexist with RUNX1 and SETBP1 mutations in myelodysplastic syndromes (MDS) and AML14." (PMID 38129572, 2023). "Mutations in ASXL1 and SETBP1 genes have been frequently detected and often coexist in myelodysplastic syndrome (MDS) and acute myeloid leukaemia (AML)." (PMID 30367089, 2018). "In addition, SETBP1 mutations have been reported to drive leukemic transformation in ASXL transcriptional regulator 1 (ASXL1)-mutated myelodysplastic syndrome (MDS)." (PMID 35898891, 2022). "Somatic mutations of SETBP1 were associated with −7/del(7q) and poor prognosis, possibly due to its gain-of-function which promotes myeloid leukemic transformation in patients with myelodysplastic syndromes (MDS) and CMML." (PMID 29225884, 2017).
myeloproliferative neoplasm (11 papers, 2017 to 2026). A clonal hematopoietic stem cell disorder, characterized by proliferation in the bone marrow of one or more of the myeloid (i.e., granulocytic, erythroid, megakaryocytic, and mast cell) lineages. "Similarly, we have retrieved from literature 245 individual somatic mutations in the SETBP1 degron, associated with different myeloproliferative disorders." (PMID 28346496, 2017).
developmental delay (10 papers, 2017 to 2025). "This study reports a case of developmental delay caused by a pathogenic SETBP1 mutation (c.1630C>T, p.Arg544Ter), which was identified through WES and validated by familial segregation analysis." (PMID 41282480, 2025). "Type III, also known as the simple type, is diagnosed in patients with the SETBP1 variant and developmental delays, with expressive language delay being the most prominent feature." (PMID 38711130, 2024). "Its strong association with developmental delay along with language impairment makes SETBP1 a new candidate gene for NDDs." (PMID 38674362, 2024). "This patient does not present any of the major congenital anomalies commonly found in SGS and, despite developmental delay, his initial developmental outcome seemed higher compared to individuals with SETBP1 mutations within the degron." (PMID 28346496, 2017). "Importantly, this study provides additional evidence that SETBP1 gene mutations may be associated with developmental delay, suggesting new directions for investigating the genetic basis of developmental disorders." (PMID 41282480, 2025). "This study reports a pediatric case of developmental delay in which WES identified a heterozygous variant (c.1630C>T, p.Arg544Ter) in the SETBP1 gene, subsequently confirmed as a de novo mutation by Sanger sequencing, leading to a definitive diagnosis of MRD29." (PMID 41282480, 2025). "The three individuals carrying the identified SETBP1 variants presented mild to severe developmental delay and lacked the cardinal features of classical SGS." (PMID 33391157, 2020). "However, in 2011, the identification of microdeletions encompassing SETBP1 in two patients with mild developmental delay led researchers to propose that haploinsufficiency of SETBP1 might underlie milder developmental impairments." (PMID 41282480, 2025). "Notably, POLR2A variants have been associated with a recently described neurodevelopmental syndrome with infantile-onset hypotonia and developmental delay with milder phenotypes attributed to haploinsufficiency, and a phenotype that shares overlapping features with SETBP1-HD." (PMID 39350244, 2024).